HLA-G (major histocompatibility complex, class I, G)
Diseases named in the same sentence as HLA-G in open-access papers (continued):
Sharing a sentence is not in itself a finding about the gene and the disease.
tumor (continued). "There was a positive association between tumoral HLA-G expression and T stage.Diffuse expression of HLA-G in tumor tissues was associated with poor OS." (PMID 33425752, 2020). "This HLA-G expression on tumor cells is accompanied by the presence of sHLA-G in the sera and is associated with bad prognosis." (PMID 32922387, 2020). "In this study it was shown that HLA-G was more frequently expressed in metastatic cells than in primary tumor lesions and the expression of HLA-G inversely associated with the frequency of tumor infiltrating immune cells." (PMID 30932005, 2019). "Due to the tumor-supporting features of HLA-G, we further analyzed the association of HLA-GEV with the presence of CTCs before therapy." (PMID 31382533, 2019). "HLA-G expression has been investigated in a variety of cancers and is correlated with worse overall survival or increased risk of tumor progression and metastases in most studies." (PMID 29564225, 2018). "The expression of HLA-G on cancer cells is also found to associate with a higher tumor grade and poor prognosis, such as in primary and metastatic ovarian tumors and primary colorectal tumors." (PMID 30061885, 2018). "Aberrant HLA-G expression in cancers has been found to be associated with advanced tumor stage, metastasis status and poor disease outcome." (PMID 30319626, 2018). "Here we further obtained direct evidence that EwS can respond to infiltration with T cells by upregulation of HLA-G: CAR T cell therapy of tumor xenografts in vivo was also associated with HLA-G expression." (PMID 29464090, 2018). "In a previous study from our own group, HLA-G expression in EwS xenografts was associated with continued tumor growth despite treatment with activated NK cells expressing GD2-specific CARs." (PMID 29464090, 2018). "Several additional cancer markers have been identified on BC-EVs including HER-2 and HLA-G, both being associated with tumor proliferation, invasiveness, drug resistance, and metastasis formation." (PMID 29632535, 2018). "We also presented the underlying mechanisms of HLA-G in tumor progression not only related to the inhibition of NK lysis, but to the specific induction of matrix metalloproteinase-15 (MMP-15) expression." (PMID 30234020, 2018). "HLA-G, a potent immune suppressive mediator firstly observed in cytotrophoblasts, has been observed in various malignancies and strongly associated with tumor immune escape, metastasis and patient survival." (PMID 28415627, 2017). "The study highlighted that HLA-G was found to be expressed at significantly higher levels in tumor tissues compared to normal tissues and this was associated with decreased levels of intratumoral CD3-positive tumor infiltrating lymphocytes." (PMID 28587243, 2017). "These phenomena explain why expression of HLA-G on cancer cells is associated with a higher tumor grade and a poor prognosis." (PMID 28781970, 2017). "An increased lesion HLA-G expression or peripheral sHLA-G levels were associated with clinical parameters such as advanced disease stage, tumor metastasis and/or worse prognosis in tumor patients." (PMID 28415627, 2017). "Previous studies showed that tumor HLA-G expression was associated with advanced stage or worse clinical outcome and its potential as a prognostic biomarker has been intensively investigated." (PMID 29296176, 2017). "Two important mechanisms in the tumor escape from the host immune recognition and destruction are the expression of HLA-G and/or the complete loss or down regulation of classical HLA class I molecules." (PMID 28781970, 2017). "Before NACT, sHLA-Gfree levels are exclusively related to estrogen receptor expression, whereas high amounts of HLA-G in EVs (sHLA-GEV) enriched from peripheral blood samples are associated with the existence of circulating stem cell-like tumor cells." (PMID 27199995, 2016).
tumor (continued). "On the contrary, an overall progressive increase in average methylation is observed from first to third trimester placenta with a decrease in HLA-G expression, while global hypomethylation has been associated with tumor progression." (PMID 27577073, 2016). "The miR-548q-mediated downregulation of HLA-G caused an increase in the ILT2+ NK cell-mediated cell lysis of the tumor cells, which was statistically significant in the E:T-ratios (1:1 and 5:1) when compared the respective mock transfectants." (PMID 27057628, 2016). "Five novel and interesting studies have addressed the correlation of different polymorphism of HLA-G gene with tumor progression." (PMID 27652273, 2016). "We suggest that therapeutic strategies should take into account that HLA-G expression in response to hypoxic tumor environment is dependent on HLA-G gene polymorphism and DNA methylation state at the HLA-G locus." (PMID 27577073, 2016). "The mechanism has been mainly related to the expression of HLA-G by tumor cells and to its release in a form associated to EVs." (PMID 26704308, 2015). "The findings of these studies clearly underlined the importance of HLA-G in tumor progression, metastasis, and as an immune escape mechanism." (PMID 26460949, 2015). "Expression of HLA-G in tumour tissues has been associated with the clinical outcome of CRC as an independent and unfavourable prognostic factor of reduced OS." (PMID 26633805, 2015). "Noteworthy, is the induced expression of HLA-G on the surface of tumor cells, which has been associated with greater tumor morbidity, tumor progression, and spreading." (PMID 25699038, 2015). "(iii) In the evasion phase, tumor cells have lost molecules important for the immune recognition and tend to express only HLA-G on the cell surface, rendering them less susceptible to effector cells." (PMID 24800261, 2014). "Human leukocyte antigen-G (HLA-G) is known to be implicated in a tumor-driven immune escape mechanism in malignancies." (PMID 24870375, 2014). "In this study, by combining the immune-related tumor markers HLA class I, HLA-G and Foxp3+, we reported an independent association between tumor immune-phenotype and patient outcome." (PMID 24997850, 2014). "Expression of HLA-G on tumour cells in malignant effusions has been demonstrated to be related to survival and proposed as a possible marker of tumour susceptibility to chemotherapy." (PMID 24987709, 2014). "The different isoforms of HLA-G have been shown to be expressed both by the tumour cell and by tumour associated macrophages/monocytes in lung cancer, melanoma, breast cancer and neuroblastoma and by glioblastoma infiltrating microglia." (PMID 24093459, 2013). "An association between raised levels of HLA-G molecules and human carcinogenesis has already been noted and their expression by certain types of tumor is well documented, though some results are controversial." (PMID 24363939, 2013). "As macrophages come into close association with tumour cells, they are exposed to high concentrations of soluble HLA-G." (PMID 24093459, 2013). "Conversely, in tumors the opposite strategy, namely downregulation of HLA-G, may be beneficial, as HLA-G expression has been directly implicated in tumor immune evasion and therapy resistance." (PMID 41445738, 2025). "They enhanced GM-CSF production, partially via HLA-G, which may promote the recruitment of tumor-associated neutrophils and macrophages and induce PD-L1 expression on these cells." (PMID 40948764, 2025). "Additionally, we examined the HLA-G expression loss in tumor tissues using immunohistochemistry (IHC), and we aimed to assess the infiltration of killer cell immunoglobulin-like receptors (KIRs) on NK cells within the tumor microenvironment." (PMID 41234446, 2025). "Among these, HLA-G and PD-L1 have been implicated in suppressing anti-tumor immune responses." (PMID 40948764, 2025).
tumor (continued). "This study analyzed the relative HLA-G mRNA expression in urine cell samples and sHLA-G serum levels and correlated them with the HLA-G 14 bp ins/del polymorphism and the selected variables including tumor grade, disease stage, BMI, and HRV parameters in BC patients." (PMID 39594832, 2024). "HLA-G expression was described in various tumors including gastric, colorectal, lung, breast, hepatocellular and pancreatic cancer as well as chronic lymphocytic leukemia and was associated with tumor progression and a worse outcome." (PMID 37781391, 2023). "However, the degree of HLA-G expression varies between tumors or within the same tumor, possibly due to the polymorphism exhibited by this molecule." (PMID 38162657, 2023). "On the other hand, the plasma sHLA-G is frequently undetectable/low in PTC patients, and its levels were not influenced by any of the assessed markers in the tumor microenvironment (BRAF or HLA-G tumor expression, BRAFV600E, and TERT mutations), as reported in this series." (PMID 37569841, 2023). "We speculate that these differences may be caused by the functional differences between membrane-bound HLA-G and soluble HLA-G isoforms, or caused by the specific tumour microenvironment." (PMID 36053326, 2023). "HLA-G expression is associated with clinical parameters such as disease stage, differentiation degree and nodular status, and contribute to create an immune tolerant microenvironment, allowing the tumor to escape immunosurveillance." (PMID 37573450, 2023). "HLA‐G is considered as an immune checkpoint protein and a tumor‐associated antigen." (PMID 37078788, 2023). "We hypothesized that the development of resistance to HLA‐G Nb‐CAR‐γδT treatment in tumor cells may be caused by altering the expression levels of HLA‐G and/or other ICPs." (PMID 37078788, 2023). "In this phase, the activity of tumor infiltrating lymphocytes (TILs) and NK cells is associated with cytotoxicity and with the production of Th1 profile cytokines (IFNγ), that increase the cell surface expression of HLA class I molecules, including HLA-G." (PMID 35154112, 2022). "Notably, the substantial lack of expression of HLA-G in normal tissues, associated with its presence on tumor cells, makes HLA-G an ideal tumor-specific target to be used also for chimeric antigen receptor (CAR) development." (PMID 35328349, 2022). "In conclusion, HLA-G expression was associated with significantly poor clinical outcome in GC patients and also correlated with parameters that reflect low immunogenicity/immunosuppression of tumours." (PMID 34361031, 2021). "Furthermore, Kaplan–Meier analysis did not reveal any statistically significant differences in OS time associated with tumour HLA-G expression, although it was unclear which patient groups were being compared with each other." (PMID 34361031, 2021). "Moreover, we found that HLA-G is expressed in a relevant proportion of human pre-treatment EwS biopsies either on the tumor cells or on infiltrating lymphocytes and associated with the presence of infiltrating T cells." (PMID 34201079, 2021). "However, none of these studies performed analyses concerning the association between tumour HLA-G expression and clinical patient outcomes." (PMID 34361031, 2021). "Significantly prolonged OS and DFS time were observed associated with tumour HLA-G expression." (PMID 34361031, 2021). "Special consideration went into whether the used methods to determine tumour HLA-G expression were indicative for the association between tumour HLA-G expression and clinical patient outcome." (PMID 34361031, 2021). "This apparent interaction between tumour HLA-class I expression, HLA-G expression and its association with clinical patient outcome may provide an explanation for the biological course of action of tumour immunoediting." (PMID 34361031, 2021). "The upregulation of HLA-G in tumors might be due to proteins associated with inflammation and secreted into the tumor microenvironment." (PMID 35111159, 2021).
tumor (continued). "Additionally, clinicopathological tumour characteristics indicative for disease progression were associated with level of HLA-G expression." (PMID 34361031, 2021). "All three studies showed significantly poor OS associated with tumour HLA-G expression." (PMID 34361031, 2021). "In summary, sHLA-G and HLA-G-bearing EVs may provide unpredictable diagnostic opportunities to monitor tumor status and progression." (PMID 34868081, 2021). "At the same time, HLA-G expressed by EwS cells could engage the receptor ILT4 on tumor-associated macrophages, resulting in acquisition of immune-suppressive properties and selective expansion of myeloid suppressor cells." (PMID 34201079, 2021). "Studies showing significant associations between tumour HLA-G expression and poor clinical patient outcome also found positive correlations between HLA-G expression and clinicopathological parameters associated with increased tumour burden, such as tumour grade, stage, depth and LNM." (PMID 34361031, 2021). "Furthermore, associations between tumour HLA-G expression and indicators of advanced cancer stages, such as advanced TNM and increased LNM, were observed in all included studies." (PMID 34361031, 2021). "Tumour HLA-G expression also showed an association with HLA-class I overexpression." (PMID 34361031, 2021). "In addition, PINK1 expression was more strongly correlated with tumor-associated macrophage markers, such as HLA-G, CD80, and CD86, in LUSC than in LIHC." (PMID 33244455, 2020). "Indeed, many publications showed the high frequency of HLA-G expression in tumor cells, correlated with clinical background associated with tumor immune escape and bad prognosis." (PMID 32922387, 2020). "Additionally, HLA-G expression levels have been associated with advanced tumor stage, metastasis status and poor diagnosis in various tumors." (PMID 32023940, 2020). "Furthermore, the HLA-G expression was associated with the tumor grade: WHO grade 3 tumors often exhibited a stronger HLA-G staining than lower grade tumors." (PMID 32993793, 2020). "Besides the loss of classical MHC class I expression, HLA-G and HLA-E expressions remained protecting tumor cells against NK cells cytotoxic response." (PMID 32922387, 2020). "In addition to direct cell–dell interactions HLA-G positive, tumor-associated macrophages (TAMs), can also secrete HLA-G, thereby promoting and supporting an immune-suppressive milieu surrounding cancer cells to further enhance immune evasion." (PMID 31013867, 2019). "Rs3869062 showed significant association with increased expression of HLA-G, which has been reported to be involved in immune recognition and might manipulate tumor specific immune responses through cytokine production." (PMID 32010612, 2019). "We conclude that tumor infiltration with T cells in EwS is associated with upregulation of HLA-G." (PMID 29464090, 2018). "Based on these pioneering studies, the hypothesis that HLA-G expression is associated with malignant transformation and tumor cell immune evasion was proposed." (PMID 30319626, 2018). "In the era of the precision medicine, the inter- and intra-tumor heterogeneity caused by complexity of the validated and even novel HLA-G isoforms, interpretation of the significance of HLA-G in cancers must be with extreme caution before their distinct roles are elucidated." (PMID 30234020, 2018). "Soluble HLA-G also causes monocyte differentiation to immunosuppressive M2 macrophages, which may be significant in a tumor microenvironment with active CMV infection." (PMID 29467963, 2018). "Importantly, whereas HLA-Gneg EwS were only scarcely infiltrated with T cells, HLA-G expression was associated with the presence of T cells in the tumor microenvironment, suggesting a causal link between T cell infiltration and upregulation of HLA-G." (PMID 29464090, 2018).
tumor (continued). "Moreover, tumor-associated macrophages (TAMs), involved in tumor progression, angiogenesis, and suppression of antitumor immunity, express surface HLA-G and secrete or shed HLA-G molecules." (PMID 28781970, 2017). "However, mechanisms underlying the individual or tumor-specific expression of HLA-G are required to be explored." (PMID 29296176, 2017). "High gene expression of HLA-G could reflect highly vascularised tumours and susceptibility to chemotherapy." (PMID 24987709, 2014). "When we combined our markers, patients showing the worst prognosis were patients with tumors bearing 2 or 3 negative prognostic markers; patients with loss of HLA class I tumor expression, weak HLA-G tumor expression and low tumor infiltration with Foxp3+ cells." (PMID 24997850, 2014). "Moreover, a better relapse-free survival was associated with a low HLA-G expression and with a high HLA-E expression, thus suggesting a divergent role of these molecules in the progression of this type of tumor." (PMID 25202308, 2014). "It has been demonstrated that tumor-associated macrophages (TAM) express HLA-G on their surface." (PMID 25202308, 2014). "Previous findings have suggested that epigenetic-mediated HLA-G expression in tumor cells may be associated with resistance to host immunosurveillance." (PMID 18498645, 2008). "Furthermore, HLA-G might serve as a possible marker for tumor susceptibility to chemotherapy and as a prognostic marker for advanced tumor stage and clinical outcome." (PMID 37630236, 2023). "In addition, the molecular mechanisms underlying the differential expression of HLA-G isoforms may be influenced by the tumour microenvironment, such as the surrounding cytokine profile." (PMID 36053326, 2023). "However, the NPS was negatively associated with HLA-G, an immune tolerance molecule that enables tumor cells to escape killing and lysis by NK cells and CTL cells, which is a previously unknown mechanism of tumor cell escape from immune surveillance." (PMID 36170029, 2022). "Tumor immune escape is associated with both, the expression of immune checkpoint molecules on peripheral immune cells and soluble forms of the human leukocyte antigen-G (HLA-G) in the blood, which are consequently discussed as clinical biomarker for disease status and outcome of cancer patients." (PMID 32973812, 2020). "However, HLA-G expression exerts opposing functions and is linked to higher tumor grade." (PMID 32993793, 2020). "In that way, the identification of the cellular source on HLA-G-bearing EVs, such as the detection of the tumor marker HER-2/neu, may offer unforeseen diagnostic opportunities to monitor the systemic health status/disease status and disease activity/progression." (PMID 27199995, 2016). "Response to pembrolizumab was observed in the patient whose tumor demonstrated 90 % PD-L1 expression, was HLA-G positive, and had tumor infiltrating lymphocytes." (PMID 41567618, 2026). "Tumor cells and stromal components upregulate inhibitory ligands including HLA-E/HLA-G and PD-L1, thereby suppressing NK cells cytotoxicity." (PMID 41562080, 2025). "We examined how HLA-G expression correlated with various clinical and pathological features, such as patient age, sex, tumor invasion depth, lymph node status, and tissue grade." (PMID 41234446, 2025). "We then explore how HLA-G modulates cytotoxic mechanisms, particularly the activity of NK cells and CTLs in tumor microenvironment." (PMID 41445738, 2025). "A bispecific T cell engager, JNJ-78306358, was recently described that simultaneously targets CD3 and HLA-G, enabling direct redirection of T cells toward HLA-G+ tumor cells." (PMID 41445738, 2025). "The HLA-G expression is upregulated in various tumor cells and is rarely observed in healthy tissues." (PMID 40584831, 2025). "Co-culture of the anti-HLA-G CAR-NK cells with tumor cells led to the activation of the Syk/Zap70 signal transduction cascade of NK cells, thereby reversing the HLA-G-mediated immunosuppressive signals." (PMID 41511303, 2025).